IL6 (interleukin 6)
Diseases named in the same sentence as IL6 in open-access papers (continued):
Sharing a sentence is not in itself a finding about the gene and the disease.
lung carcinoma (continued). "Moreover, miR-19a or miR-19b-1 overexpression reduced IL6 expression in the lung cancer and NPC cells examined." (PMID 32308549, 2020). "An increased level of IL6 correlates with the poor prognosis and survival of lung cancer patients." (PMID 32219066, 2020). "Additionally, the treatment of lung carcinoma cells with cucurbitacin I inhibited IL-6 induced STAT3/JAK2 signalling." (PMID 32731620, 2020). "IL-6, JUN, EGFR, and MYC were shown to associate with the survival of lung cancer patients." (PMID 32595734, 2020). "We further confirmed that TIM‐4 knockdown could inhibit IL‐6‐enhanced migration, invasion and EMT of lung cancer cells in vitro, as well as IL‐6‐enhanced lung cancer metastasis in vivo." (PMID 32020709, 2020). "Finally, we detected the effects of TIM‐4 on IL‐6 promoting lung cancer EMT capacity by qPCR and Western blot, migratory and invasive activities by transwell assay, respectively." (PMID 32020709, 2020). "However, three hub genes JUN, FGF2, CCND1 and IL6 expressed fewer mRNAs in lung cancer tissues than normal lung tissues." (PMID 32210363, 2020). "Evidences indicate that increase of IL-6 was not only occurred in liver ablation, researches focus on lung cancer, including primary lung cancer and pulmonary metastases demonstrated that serum IL-8, IL-1β, IL-6, IL-10, IL-12 and TNF-α were significantly raised after radiofrequency thermal ablation." (PMID 32847533, 2020). "Although IL-6 is implicated in the malignancy of lung cancers, the association of DDIAS in IL-6–mediated signaling has not been investigated." (PMID 31900385, 2020). "Subsequently, 50 ng/mL IL‐6 was used to stimulate lung cancer cells for 24 hours." (PMID 32020709, 2020). "In addition, enforced miR-19a or miR-19b-1 expression suppressed IL-6 production by lung cancer and nasopharyngeal carcinoma (NPC) cells." (PMID 32308549, 2020). "As expected, we observed that increased IL6 expression in FAS knockdown lung cancer cells." (PMID 32963220, 2020). "Moreover, we identified glycogen synthase kinase 3 beta (GSK3B) and interleukin-6 (IL-6) as novel potential therapeutic targets in colon and lung cancers, respectively, using organoids, 3D structures derived from the CSC-like cells." (PMID 33008481, 2020). "Moreover, increased IL-6 serum levels correlate with increased pulmonary toxicity for lung cancer after RT." (PMID 30658426, 2019). "The pro-inflammatory cytokine IL-6 is of relevance in lung cancer biology, pathology, and therapy, especially as it interacts with and activates the signal transducer and activator of transcription (STAT)-3, which is constitutively activated in various types of malignancies." (PMID 31547048, 2019). "Regarding lung cancer, blocking of IL-6 trans-signaling using sgp130Fc—which is a fusion protein of sgp130 and the crystallizable fragment of immunoglobulin G1—or the anti-IL-6R monoclonal antibodies 1F7 and 25F10, ameliorated tumourigenesis in the oncogenic KrasG12D-induced LAC mouse model." (PMID 31438559, 2019). "Additional studies are needed to determine whether targeted inhibition of innate cytokines, such as IL-17C or IL-6, with therapeutic antibodies enhance the response to PD-1 blockade in lung cancer." (PMID 31316109, 2019). "Since IL-6 and TNF-α can predict the occurrence and recurrence of hepatocellular carcinoma, TNF-α, IL-1, IL-6, and IL-8 might be used as biomarkers for prevention and prediction of lung cancer." (PMID 31832112, 2019). "Growth and migration of lung cancer cells were obviously promoted in the presence of media derived from three types of asbestos (chrysotile, amosite, and crocidolite)-exposed lung fibroblasts, which contained high levels of IL-6 and IL-8." (PMID 31491033, 2019).
lung carcinoma (continued). "Future studies on naïve tumor samples or LUSC and LUAD cellular models, where the IL6 gene can be modulated by overexpression or silencing, could shed light on its role within the two lung cancer types." (PMID 31429720, 2019). "In addition, aberrant Akt was found to contribute to maintaining stemness through a NF-kB/IL-6/STAT3 pathway in lung cancer cells." (PMID 31696055, 2019). "In addition to IL-6, breast and lung cancer cells are known to rely on autocrine signaling by IL-11 for their tumor-associated functions, including survival, invasion, and metastasis." (PMID 31491838, 2019). "Interestingly, this occurred even when the pathway was overstimulated with its ligand interleukin 6 (IL-6), which is frequently overexpressed in lung cancer patients who show poor clinical outcomes." (PMID 31412593, 2019). "The number of penetrating lung cancer cells was significantly increased after treatment with aADSC-CM and was reduced when cancer cells were cultured with IL-6-neutralizing antibody, confirming that IL-6 is essential for the invasion-promoting effect of aADSCs." (PMID 31196220, 2019). "Treatment with Canakinumab, a monoclonal antibody against IL-1β, led to a dose-dependent reduction in the concentrations of the inflammation markers high-sensitivity C-reactive protein and interleukin 6 (IL-6) as well as a reduction in lung cancer incidence and mortality." (PMID 30767158, 2019). "A recent study by Caetano and colleagues demonstrated that female animals, in the context of Il-6 and Stat3 pro-tumor inflammatory signaling, displayed differential anti-lung cancer immune responses, evidenced by levels of tumor infiltrating lymphocytes, compared with males." (PMID 31001473, 2019). "K-ras activated lung cancer cells orchestrate the TME through secreting cytokines IL-6, IL-10, IL-17, TGF-β, and TNF, which can either suppress antitumor T cells directly or stimulate immune cells such as MDSCs, Th17s, M2 macrophages, and Tregs to inhibit Th1/CD8+ T cell function." (PMID 32039025, 2019). "Our data show that IL-6 levels were higher in the lung cancer tissues of smokers than in those of non-smokers and that ΔNp63α expression was positively associated with IL-6 levels in these tissues." (PMID 31367260, 2019). "Furthermore, it is assumed that in cancer cells the AhR-mediated transcription of IL6 leads to the autocrine activation of IDO expression via STAT3 (AhR-IL6-STAT3 loop), which is associated with a poor prognosis in lung cancer." (PMID 31417567, 2019). "Interleukin-6 (IL-6) is a proinflammatory cytokine with pleiotropic functions in regulating the growth and differentiation of different types of cancer cells, including breast, colon, and lung cancers." (PMID 31491838, 2019). "To examine whether T21 was also able to block STAT3 signaling after stimulating with one of its upstream ligands, we first analyzed the IL-6 effects on STAT3 phosphorylation in lung cancer cells." (PMID 31412593, 2019). "In addition, TRAPs from the hepatic carcinoma Hepa1–6, lung cancer LLC or lymphoma EL4 cells also potently enhanced IL-6 secretion in CD4+ T cells." (PMID 31300052, 2019). "This indicates that in the process of radiation-induced lung cancer resistance induced by NRP1, both inflammatory reactions and the radiosensitivity of lung cancer cells may be reduced by regulating IL-6 and IL-8 in the tumor inflammatory microenvironment." (PMID 31417646, 2019). "Treatment with an IL6-neutralizing antibody completely eliminated chemoresistance of ovarian and lung cancer stem cells in vivo, suggesting that targeting IL-6 could be an effective strategy in eliminating bCSCs as well." (PMID 31450577, 2019). "Ablation of IL-6 or STAT3 suppressed the extent of lung cancer in this model." (PMID 31694340, 2019). "In particular, IL-6 levels have been found increased in nearly 40% of lung cancer patients." (PMID 31412593, 2019).
lung carcinoma (continued). "Similarly, IL-6 have been found to be increased in fibroblasts cultured with the CM from lung cancer." (PMID 30744595, 2019). "IL-6 is the most prominent target of STAT3 and is associated with poor prognosis of lung cancer." (PMID 30634502, 2019). "In addition, ERβ expression affects the aggressive of lung cancer cells via E2 regulation of IL6 expression." (PMID 29970138, 2018). "Previous studies have reported that IL‐6 levels are higher in lung cancer patients than in healthy people 35, therefore, CTAP III/CXCL‐7 may be derived from the secretion of mesenchymal cell." (PMID 29356357, 2018). "Moreover, in mice that overexpress APOC1, levels of IL-6 and IL-1 beta are elevated, and in lung cancer patients." (PMID 29541006, 2018). "Autocrine IL6 and ERβ may represent a positive feedback loop, and synergistic inhibition of ERβ and IL6 may serve as a potential target for prognostic assessment and therapeutic intervention in lung cancer." (PMID 29970138, 2018). "Moreover, higher levels of IL-6 exists in NSCLC patients and shows an upward trend and IL-6 is associated with the pathogenesis and progression of lung cancer." (PMID 30369945, 2018). "Blockade of IL6 suppresses proliferation of lung cancer stem cells." (PMID 29970138, 2018). "Here, we also observed that USP24 in lung cancer cells increased IL-6 expression." (PMID 30266897, 2018). "In lung cancer cells, the IL-6 promoter activity was decreased after USP24 knockdown." (PMID 30266897, 2018). "We also clarify the difference in each ERβ subtype for E2 promoting IL6 expression, suggesting that ERβ/IL6 might be potential targets for prognostic assessment and therapeutic intervention in lung cancer." (PMID 29970138, 2018). "IL6/ERβ expression were significantly increased in lung cancer." (PMID 29970138, 2018). "Ectopic expression of IL6 stimulated by E2 contributes to a poor outcome in lung cancer." (PMID 29970138, 2018). "Expression of ERβ/IL6 in 289 lung cancer samples was assessed by immunohistochemistry." (PMID 29970138, 2018). "Interestingly, we found that USP24 stabilizes p300 to manipulate the acetylation level of histone 3 in the IL-6 promoter region in M2 macrophages and lung cancer cells." (PMID 30266897, 2018). "We found E2 up-regulate IL6 expression and promote lung cancer." (PMID 29970138, 2018). "IL6 has been similarly reported to be overexpressed in lung cancer." (PMID 29970138, 2018). "To further explore whether ectopic expression of ERβ affects IL6 expression and aggressiveness of lung cancer cells, we chose two cell lines, A549 and H1793, to knockdown and overexpress ERβ." (PMID 29970138, 2018). "In line with an important role of IL-6 trans-signaling, autophagy acceleration in response to lung cancer patient sera was significantly reduced when trans-signaling was inhibited by soluble gp130Fc (Student t-test, p = 3.11e-05, 8% reduced autophagy activity, n = 7)." (PMID 28515477, 2017). "To evaluate whether IL-6-expressing lung cancer cells exist in human lung cancer tissues, we performed in situ hybridization for IL-6 using 10 lung adenocarcinoma tissue specimens from 8 patients of various backgrounds." (PMID 28951614, 2017). "First we detected the endogenous IL-6 level in CAFs and lung cancer cells." (PMID 29100297, 2017). "Given the stimulatory role of IL-6 on JAK/STAT signaling, IL-6/JAK/STAT3 signaling may be involved in lung cancer progression." (PMID 28819126, 2017). "Taken together, CAFs may induce lung cancer cell EMT via secreting IL-6 that activate STAT3 and subsequently inhibit miR-33b which locates in SREBP1 gene." (PMID 29383119, 2017). "Mitochondrial dysfunction and oxidative stress of repeated exposure to urethane associated with over stimulation of IFN-γ-producing cells, CD11b + Gr-1 + phenotype, overexpression of NF-кB, COX-2, STAT3, IL-6 and cyclin D1 resulted in chronic inflammation and lung cancer." (PMID 28240047, 2017).
lung carcinoma (continued). "Other studies analyzed the IL-6 expression in tumor tissue, plasma and bronchoalveolar lavage, and found a correlation with progression, resistance to anti-tumor therapies and poor survival of patients with lung cancer." (PMID 28715437, 2017). "Recently, IL-6 blockade was shown to inhibit mutant KRAS driven lung cancer, indeed several studies have shown increased IL-6 expression in lung tumors with mutant KRAS —evidence of this relationship can also be observed from a parallel study on-going in our group." (PMID 28402963, 2017). "The current results raise the hope that IL-6 signal blockade and conventional chemotherapy may be used as a combination therapy targeting both lung cancer stem cells and bulk cancer cells." (PMID 28951614, 2017). "CAFs and NFs expressed significant higher level of IL-6 than lung cancer cells." (PMID 29100297, 2017). "Additionally, we also investigated the effect of STAT3 pathway inhibition in lung cancer cells to understand the importance of IL-6/JAK/STAT3 pathway." (PMID 28830450, 2017). "In addition, the levels of both miR-218 host genes and the components of IL-6/STAT3 pathway correlated with prognosis of lung cancer patients." (PMID 28830450, 2017). "Both IL-1β and IL-6 are well known to up-regulate the aromatase gene transcripts and its activity in several types of cells, including osteoblasts (IL-1β) and fibroblasts derived from lung cancer (IL-6)." (PMID 29039776, 2017). "We therefore investigated whether the association with survival of the IL-6 plus IL-17A classifier and the IL-6, CRP and IL-17A classifier was specifically associated with survival in stage IA lung cancer patients." (PMID 28402963, 2017). "MiR-218 acts as a tumor suppressor in lung cancer via IL-6/STAT3 signaling pathway regulation." (PMID 28830450, 2017). "Besides its direct protumorigenic effects on tumor cells via STAT3/Akt pathways, IL-6 signaling has indirect effects by promoting an immunosuppressive tumor microenvironment, which has been described in a Kras-induced lung cancer mouse model." (PMID 28878242, 2017). "Having found that IL-6 induces autophagy via trans-signaling and that tumor IL-6 mRNA expression is a predictor of poor prognosis in lung cancer patients we asked if there is an association between IL-6 levels and the autophagy inducing activity of the CNLCB lung cancer patient sera." (PMID 28515477, 2017). "We evaluated the effects of IL-6 on the lung cancer organoid construction ability." (PMID 28951614, 2017). "Indeed, a previous study has demonstrated that M. pneumoniae infection induces proinflammatory cytokine expression in human lung carcinoma cell line (A549) including IL1β, IL6, IL8, and TNFα." (PMID 28553017, 2017). "In particular, in vitro evidence that the rs1800797 variant modulated IL6 expression supports a role for IL-6 in pathogenic mechanisms associated with squamous cell lung cancer in uranium miners and with lung cancer in never smokers." (PMID 26372664, 2016). "Moreover, the inhibition of IL-6 signaling is able to slow the growth of colon and lung cancers, unveiling a role for IL-6 as a possible therapeutic target." (PMID 27851822, 2016). "We herein report a case of complete resection of right pleomorphic lung cancer producing IL-6." (PMID 27659803, 2016). "An IL6 promoter variant was associated with lung cancer in uranium miners and never smokers in two external study populations." (PMID 26372664, 2016). "We experienced a case of pleomorphic lung cancer producing IL-6." (PMID 27659803, 2016). "In particular, IL6 blockade significantly inhibited lung cancer promotion." (PMID 27833137, 2016). "The IL-6 -573 SNP is a transversion (G → C) that was reported as a genetic risk factor of lung cancer risk in Singaporean Chinese non-smoking females." (PMID 27220278, 2016).
lung carcinoma (continued). "Our previous studies showed that MMP-13 mediate IL-6 increasing lung cancer metastasis via ATM activation, therefore, we speculate that MMP-13 might be a critical potential target for TNF-α augmenting lung cancer migration." (PMID 27556690, 2016). "There were a few cases reported that pleomorphic lung cancer produced IL-6." (PMID 27659803, 2016). "In preclinical studies, siltuximab inhibited IL-6–induced activation of ovarian cancer cells, inhibited IL-6–induced survival of advanced prostate cancer, suppressed lung cancer growth in mouse xenograft models, and enhanced melphalan cytotoxicity in a preclinical multiple myeloma model." (PMID 26840088, 2016). "In addition, recent studies in our laboratory revealed the importance of IL-6 in rendering radioresistance to CD133+ cells of lung cancer (manuscript in press)." (PMID 26675547, 2016). "As EMT could be affected by the composition and structure of ECM, the findings that ATM phosphorylation increases MMP-3/MMP-13 expression and promotes lung cancer metastasis indicate that the phosphorylation of ATM might be involved in IL-6 promoting EMT." (PMID 26528698, 2015). "Moreover, the inhibition of ATM phosphorylation not only abrogates IL-6 increased, MMP-3/MMP-13 mediated cell migration in vitro, but also suppresses IL-6 correlating lung cancer metastasis in vivo." (PMID 26528698, 2015). "Our previous study reveals that IL-6 contribute to lung cancer chemotherapeutic resistance." (PMID 26528698, 2015). "The effect of IL-6 on ATM raises the question of whether ATM activation is involved in IL-6 correlated lung cancer metastasis." (PMID 26528698, 2015). "Interleukin 6 is secreted by macrophages and also by T cells (in the context of chronic inflammation) and has been clearly implicated both in the pathogenesis of COPD and in lung cancer." (PMID 26220864, 2015). "Higher level of interleukin-6 (IL-6) existed in lung cancer patients and mutant EGFR and TGFβ signal requires the upregulation of IL-6 through the gp130/JAK pathway to overactive STAT3, an oncogenic protein which has been considered as a potential target for cancer therapy." (PMID 26166037, 2015). "While Erk1/2-NF-κB pathway was reported to be partially involved in inflammatory factors TGF-β1, TNF-α and IL-6 correlated lung cancer invasion, p38-NF-κB and STAT3-NF-κB pathways were demonstrated to inhibit miR-365 expression and regulate IL-6 repressing miR-98 levels respectively." (PMID 26528698, 2015). "To address this speculation, we used IL-6 to activate STAT3 in lung cancer cells, and found that IL-6 significantly induced phosphorylation of STAT3 and suppressed crizotinib-induced autophagy." (PMID 26384345, 2015). "Modulation of this protein has not previously been linked with lung cancer or radiotherapy but it is known that it can be expressed by lung epithelial cells upon stimulation by cytokines like IL-6." (PMID 26425690, 2015). "All these findings demonstrate that IL-6 inducing ATM activation increases the expression of MMP-3/MMP-13, augments the abilities of cell migration and promotes lung cancer metastasis, indicating that ATM is a potential target molecule to overcome IL-6 correlated lung cancer metastasis." (PMID 26528698, 2015). "Furthermore, we currently experienced and described a patient in whom tocilizumab, anti-IL-6 receptor antibody, dramatically alleviated cachexia induced by IL-6 over-expressing lung cancer." (PMID 25010770, 2014). "Various studies have reported elevations in granulocyte colony-stimulating factor (G-CSF), granulocyte-macrophage colony-stimulating factor (GM-CSF), and interleukin-6 (IL-6) in tumors of the cervix, pancreatic cancer, hepatocellular carcinoma, and lung cancer." (PMID 25223869, 2014).